FGF23 (fibroblast growth factor 23)
Diseases named in the same sentence as FGF23 in open-access papers (continued):
Sharing a sentence is not in itself a finding about the gene and the disease.
hyperphosphatemia (continued). "The CKD-MBD, characterized by the triad of hyperphosphatemia, high FGF23 levels and αKlotho deficiency is central to the pathophysiology of CKD-related cardiomyopathy, so that it can be considered part of the CKD-MBD puzzle." (PMID 30087898, 2018). "In these studies, LVH correlated with αKlotho deficiency state, hyperphosphatemia, FGF23 levels and age." (PMID 30087898, 2018). "Serum phosphate levels inversely correlate with the lifespan of diverse species and hyperphosphatemia has been linked with premature aging phenotype in Klotho deficient mice and in FGF23 KO mice." (PMID 30271655, 2018). "Clinical and experimental studies demonstrated that high FGF23 serum levels, hyperphosphatemia, and klotho deficiency are strongly associated with cardiovascular complications in CKD patients." (PMID 29892269, 2018). "The pathogenic mechanisms of the components of CKD-MBD include VC, loss of renal klotho, hyperphosphataemia, osteodystrophy, vitamin D deficiency, increased FGF23, cardiovascular disease, and hyperparathyroidism." (PMID 30348110, 2018). "The sequel of 1α-hydroxylase overexpression are elevated 1,25(OH)2D3 levels, causing hypercalcemia, hyperphosphatemia, ectopic calcifications, impaired bone mineralization, and early lethality in αKlotho and Fgf23 deficient mice." (PMID 29892265, 2018). "Hyperphosphataemia associated with FGFR inhibition appears to be mediated by FGF23 signalling through FGFR1." (PMID 28972963, 2017). "For example, hyperparathyroidism, hypercalcemia, hyperphosphatemia, and elevated fibroblast growth factor 23 (FGF23) are associated with cardiovascular morbidity and mortality." (PMID 27003153, 2017). "One of the safety concerns for selective FGFR inhibitors from preclinical toxicity studies has been hyperphosphataemia, caused by loss of FGF23 signalling, resulting in calcification of tissues." (PMID 28070720, 2017). "ENU-derived kl203X/203X mice were confirmed as a model for klotho deficiency as they had markedly reduced renal Kl expression in association with hyperphosphataemia, raised circulating 1,25 dihydroxyvitamin D and FGF23 concentrations, and widespread EC." (PMID 25860694, 2015). "The results of the present study were consistent with previous studies and demonstrated that high levels of FGF-23 were closely associated with hyperphosphatemia in MHD patients." (PMID 24669256, 2014). "Ca2+ homeostasis is altered in the majority of these patients, manifested predominantly as hypocalcemia, hyperphosphatemia, vitamin D deficiency, FGF23 elevation (coupled with Klotho deficiency) and secondary hyperparathyroidism." (PMID 23760058, 2013). "The association between chronic hyperphosphatemia and FGF-23, and dietary phosphate intake and FGF-23, is well documented in both humans and animal models." (PMID 23666413, 2013). "On the other hand, defects or mutations in Fgf23 or Klotho resulted in hyperphosphatemia, premature aging, and the formation of ectopic calcifications." (PMID 22879941, 2012). "Hyperphosphatemic familial tumoral calcinosis (HFTC) is a rare autosomal recessive disorder characterized by ectopic calcifications in periarticular soft tissues due to mutations in genes such as GALNT3, FGF23, or KL, leading to FGF23 deficiency or resistance and subsequent hyperphosphatemia." (PMID 40524990, 2025). "Moreover, hyperphosphatemia leads to compensatory elevation of fibroblast growth factor 23 and parathyroid hormone, which can cause left ventricular hypertrophy, renal anemia, and immune dysfunction." (PMID 40236452, 2025). "The hyperphosphatemia and elevated fibroblast growth factor 23 (FGF23) caused by SHPT may induce brain edema by disrupting cerebral vascular autoregulation and may also inhibit neuronal energy metabolism." (PMID 41332466, 2025). "Not only hypocalcemia could be linked to this alteration but also chronic hyperphosphatemia which determines an increase in the phosphaturic factor: fibroblast growth factor 23 (FGF-23)." (PMID 40346324, 2025).
hyperphosphatemia (continued). "In addition to the Klotho gene mutation, mice with FGF23 deficiency have shorter lifespans, high serum 25-OH-D3, hyperphosphataemia, and hypercalcaemia." (PMID 38396804, 2024). "In CKD and hyperphosphatemia, the FGF23/αKlotho axis is linked to uremic vasculopathy." (PMID 35806367, 2022). "Furthermore, the 25-OHD deficiency is associated with the depletion of FGF-23 (Fibroblast Growth Factor-23), which leads to hyperphosphatemia." (PMID 35684085, 2022). "Disturbance of harmony among these factors, either solo or in alliance, may provoke phosphorus disproportion, and the inhibition of the FGF23 Klotho system can cause hyperphosphatemia with widespread tissue injury instigated by hyperphosphatemia." (PMID 36105908, 2022). "In addition, hyperphosphatemia-induced FGF-23 elevation and klotho deficiency can also be therapeutic targets for uremic cardiomyopathy." (PMID 35903671, 2022). "Hypocalcemia is associated with low FGF23 levels as a study of Gcm2−/− mice characterized by hypocalcemia, hyperphosphatemia, and low calcitriol and PTH levels and Cyp27b1−/− mice with hypocalcemia, hypophosphatemia, and low 1,25(OH)2D3 but high PTH levels has revealed." (PMID 35084563, 2022). "Whether hyperphosphatemia and/or associated changes in metabolic regulators, including elevations of fibroblast growth factor 23 (FGF23) directly contribute to specific complications of CKD is uncertain." (PMID 35302487, 2022). "Klotho deficient mice are completely resistant to FGF23 and thus develop hyperphosphatemia." (PMID 35928251, 2022). "However, multivariate Cox regression analysis in our study showed that increased FGF‐23 remained a significant risk factor for development of hyperphosphatemia after adjusting for CKD stage (ie, magnitude of GFR)." (PMID 34418162, 2021). "It is, however, unknown whether acute and severe hyperphosphatemia might cause a much greater FGF-23 release in order to overcome the FGF-23 resistance described in this study." (PMID 34884774, 2021). "In our study, increased serum FGF‐23 concentrations were significantly associated with the risk of developing subsequent hyperphosphatemia, suggesting that phosphate already may be accumulating in dogs with normophosphatemic CKD." (PMID 34418162, 2021). "On the other hand, FAM20C deficiency has opposing effects on FGF23 and phosphate (hyperphosphatemia and low FGF23) and could counteract hypophosphatemia and FGF23 elevation in RS due to its variability in patients." (PMID 34360805, 2021). "In rats, dietary induced hyperphosphatemia also caused increasing FGF23 concentrations." (PMID 33606750, 2021). "Future research that investigates whether a decrease in FGF‐23 concentrations prevents or delays the onset of hyperphosphatemia and associated progression is needed." (PMID 34418162, 2021). "Therefore, a more precise cut‐off for the FGF‐23 concentration that is associated with the risk of the development of hyperphosphatemia and CKD progression is needed." (PMID 34418162, 2021). "Collectively these results suggest that serum FGF23 may be associated with hypomagnesemia in addition to the well-established association with hyperphosphatemia." (PMID 32074140, 2020). "Klotho-/- and fgf23-/- deficient mice developed identical phenotypes, characterized by accelerated aging, a severe hypercalcemia and hyperphosphatemia, and subsequent multiple organs dysfunction such as atherosclerosis, ectopic calcifications, bone demineralization, skin atrophy, and emphysema." (PMID 32570781, 2020). "Thus, renal klotho loss, hyperphosphatemia, vitamin D deficiency, and an increase in FGF-23 are pathogenic mechanisms of hyperparathyroidism progression." (PMID 32192220, 2020).
hyperphosphatemia (continued). "Deregulations in bone and mineral metabolism, including hyperphosphatemia, 25-hydroxy vitamin D3 (25[OH]-vitamin D3) deficiency, hyperparathyroidism, and high levels of the phosphaturic hormone fibroblast growth factor 23 (FGF23), have been associated with adverse outcomes in various populations." (PMID 32506135, 2020). "Indeed, the phenotypes of FGF23 and α-klotho deficiency are very similar, with hyperphosphataemia and increased synthesis of 1,25(OH)2D3, and indicate the cooperative action of α-klotho and FGF23 in a common signalling pathway." (PMID 30393837, 2019). "Consequently, ESKD patients commonly exhibit hyperphosphatemia, FGF23 excess, 1,25(OH)2D3 deficiency, and sHPT." (PMID 31698866, 2019). "Herein, we present a review that addresses not only the development of the understanding of CKD-related cardiomyopathy pathophysiology, but also explores the recent data that identify the triad of hyperphosphatemia, high FGF23 levels and αKlotho deficiency as playing a central role on it." (PMID 30087898, 2018). "Moreover, even after correcting hyperphosphatemia due to dietary phosphate restriction, and consequently reducing FGF-23 levels, LVH persisted in αKlotho deficiency CKD animals." (PMID 30087898, 2018). "There are examples of asymptomatic hyperphosphatemic children, who developed HFTC some years after hyperphosphatemia was first identified, and in one family, a small child, with homozygous mutation in FGF23, was hyperphosphatemic but asymptomatic, in contrast to her older sister with HFTC." (PMID 25249269, 2014). "FGF23 mutationsassociated with FTC cause hyperphosphataemia through effects on expression of thesodium-phosphate co-transporter in the kidney and small intestine, and throughincreased activation of vitamin D due to increased renal expression of CYP27B1(25-hydroxyvitamin-D 1 alpha hydroxylase)." (PMID 21533022, 2011). "Similar increases in Ank and Enpp1 expression by mouse osteoblasts by extracellular Pi have been previously noted and may, along with decreased local phosphatase expression, contribute to the accumulation of unmineralised osteoid observed in Fgf23-deficient mice, despite a marked hyperphosphatemia." (PMID 40791815, 2025). "Furthermore, hyperphosphatemic familial tumoral calcinosis (HFTC), a rare and debilitating disease, results from impaired FGF23-mediated phosphate regulation, causing FGF23 deficiency or resistance, resulting in hyperphosphatemia and heterotopic calcifications." (PMID 39781450, 2025). "Thus, early studies from Dr. Wolf’s laboratory showed that, although increased FGF23 levels may prevent hyperphosphatemia, they caused an over-suppression of active vitamin D synthesis, which could have detrimental consequences." (PMID 35807756, 2022). "Similarly, knockout of the Fgf23 of αKlotho genes in mice leads to early lethality caused by unleashed production of 1,25(OH)2D, hypercalcemia, hyperphosphatemia, and ectopic calcifications, a phenotype that can be rescued by concomitant ablation of vitamin D signaling." (PMID 36501215, 2022). "High levels of FGF23 and hyperphosphatemia may cause damage to cochlea’s capillary, leading to cochlear sclerosis, and may also affect the enzymatic activity and ion exchange in the inner ear and reduce the excitability of cochlear neurons (Khodeir, Okda & Abdalal, 2019)." (PMID 34721981, 2021). "Therefore, calcitriol excess might be a dominant driver of hyperphosphatemia more than loss of FGF23 itself in Fgf23−/− mice." (PMID 33731726, 2021). "Moreover, because of the loss of FGF23 function, Klotho-deficient mice show similar phenotypes to those of Fgf23-null mice, such as ectopic calcification, elevated serum 1,25(OH)2D concentrations, and hyperphosphatemia." (PMID 30627598, 2019).
hyperphosphatemia (continued). "The present article reports, in a 67-year-old woman with hyperphosphatemia undergoing hemodialysis treatment, the identification of a novel heterozygous deletion variant in the KL gene (p.Ile348Phefs*28), possibly degraded by mRNA decay, that affects FGF23 signaling and leads to haploinsufficiency." (PMID 31013726, 2019). "Moreover, conditional deletion of α-KL from the DT using Ksp-Cre (α-KlDT-cKO) results in hyperphosphatemia and increased expression of vitamin D regulatory enzymes in association with elevated FGF-23 levels, indicating that loss of α-KL in the distal tubule can affect proximal tubule functions." (PMID 26839958, 2016). "In CKD, decreased kidney function and reduced responsiveness to the endocrine regulators result in hyperphosphatemia, that is accompanied by compensatory increases in serum levels of FGF23 and PTH and decreases in vitamin D." (PMID 40471241, 2025). "In the mouse model developed by Ichikawa and colleagues, the ablation of GALNT3 in exons 2 and 3 led to decreased circulating intact Fgf23 levels with hyperphosphatemia, despite that high levels of Fgf23 were found in bone." (PMID 40149415, 2025). "Key drivers of CVD in CKD include hyperphosphatemia and elevated levels of fibroblast growth factor-23 (FGF23), and recent studies have highlighted the role of the Klotho protein in mitigating these risks." (PMID 41141519, 2025). "Burosumab, a recombinant human IgG1 monoclonal antibody against FGF23, led to hyperphosphatemia after one dose of 60 mg requiring dose downtitration, and TmP/GFR normalized after 3 doses (1.14 mmol/L [0.84-1.23 mmol/L])." (PMID 41445556, 2025). "As a result, FGF23 plays a crucial role in maintaining the balance of P within the body, preventing the onset of hyperphosphatemia, and ensuring optimal bone mineralization." (PMID 39982925, 2025). "The biochemical parameters of mineral bone disorders including increased fibroblast growth factor 23 (FGF23), hyperphosphatemia, hypocalcemia, elevated parathormone (PTH), and 1,25-dihydroxy vitamin D3 deficiency, were frequently observed in CKD." (PMID 40421989, 2025). "PTH and FGF-23 cannot do their phosphaturic effects, resulting in hyperphosphatemia due to further elevations in iPTH and FGF-23." (PMID 40612843, 2025). "One dose of 60 mg burosumab, an anti-FGF23 antibody, led to hyperphosphatemia requiring dose titration and 3 doses of burosumab normalized renal tubular maximum reabsorption rate of phosphate relative to glomerular filtration rate." (PMID 41445556, 2025). "Fgf23−/− mice with hyperphosphatemia develop calcifications in the testis and epididymis as well as spermatogenic arrest." (PMID 40471241, 2025). "This renal resistance, combined with hyperphosphatemia, forces a massive compensatory rise in FGF23." (PMID 41515987, 2025). "Knockout mice of the FGF23 gene exhibit hyperphosphatemia and high serum 1,25(OH)2D, presenting a complex phenotype characterized by premature aging features such as thymus and spleen atrophy." (PMID 40529693, 2025). "Both the phosphaturic and the 1,25(OH)2D3-lowering effect of FGF-23 protect against hyperphosphatemia by increasing urinary elimination of phosphate and reducing intestinal phosphate absorption, respectively." (PMID 40362897, 2025). "When estimated GFR falls below 30 mL/min/1.73 m2 (CKD stages 4 + 5), renal failure no longer adequately guarantees renal P excretion despite increasing values of PTH and FGF23, thus leading to hyperphosphatemia." (PMID 40565034, 2025). "In patients with renal insufficiency who develop hyperphosphatemia, there is often accompanying hypocalcemia, elevated fibroblast growth factor-23 (FGF-23) levels, and decreased active vitamin D levels." (PMID 40810070, 2025). "We have recently shown that chronic high phosphate load in mice leads to hyperphosphatemia with increased FGF23 levels and progressive tubular injury, tubulointerstitial fibrosis, and kidney inflammation." (PMID 41384828, 2025).
hyperphosphatemia (continued). "Hyperphosphatemia and hypocalcemia, resulting from impaired renal activation of vitamin D, trigger increased production of FGF-23 and parathyroid hormone (PTH), leading to renal secondary hyperparathyroidism (RSHP)." (PMID 41295735, 2025). "The condition occurs due to a relative deficiency or resistance to fibroblast growth factor 23 (FGF23), resulting in hyperphosphatemia." (PMID 40524990, 2025). "Iron overload in β-TM leads to reduced FGF-23 levels, which disrupts the normal P regulation mechanisms by increasing renal reabsorption of P with subsequent hyperphosphatemia." (PMID 39982925, 2025). "The degree of VC is significantly negatively correlated with bone density, reflecting systemic mineral metabolism disorders such as hyperphosphatemia, elevated FGF-23, and abnormal vitamin D levels." (PMID 41140655, 2025). "This deficiency, which mimics the severe mineral imbalance of a Klotho knockout, renders the kidney resistant to the phosphaturic actions of FGF23, which is a key mechanism for the resulting hyperphosphatemia." (PMID 41515987, 2025). "In dogs, FGF-23 also appears to predict the development of hyperphosphatemia and progression of CKD." (PMID 39113723, 2024). "In patients with progressive CKD, phosphate retention, hyperphosphatemia, higher levels of FGF-23 and low expression of klotho are observed." (PMID 39113723, 2024). "Other studies highlighted the role of FGF-23 in predicting the progression ofCAC, also independently from hyperphosphatemia, LVH and cardiachypertrophy." (PMID 39076335, 2024). "It is only when maternal hyperphosphatemia was induced through dietary phosphate loading that a role for FGF23 to protect against fetal hyperphosphatemia was detected." (PMID 38577520, 2024). "Hyperphosphatemia is usually accompanied by the secretion of FGF23, a phosphaturic hormone that is not only inducible by acute and chronic inflammatory factors but also associated with inflammation, as shown in several clinical studies." (PMID 38175251, 2024). "In an effort to counterbalance hyperphosphatemia, serum levels of FGF23 and PTH rise and 1,25D levels are reduced, which are hallmarks for CKD." (PMID 38791164, 2024). "Galnt3−/− mice exhibited hyperphosphatemia and hypercalcemia, and the intact Fgf23 was about 40% that of wild-type mice." (PMID 38396954, 2024). "As the renal function deteriorates, hyperphosphatemia and low vitamin D favour hyperparathyroidism, which appears to occur after FGF23 rises to maladaptive levels in patients with ESKD." (PMID 39339698, 2024). "Prolonged hypocalcemia, hyperphosphatemia, reduced calcitriol, and heightened fibroblast growth factor-23 (FGF-23) levels all contribute to increased synthesis and release of PTH." (PMID 39165274, 2024). "Although both Galnt3−/− mice and Fgf23−/− mice showed hyperphosphatemia and hypercalcemia, the bone phenotypes in Galnt3−/− mice were quite different from those in Fgf23−/− mice." (PMID 38396954, 2024). "Hyperphosphatemia is typically seen in the later stages of this pathway, likely when the phosphaturic signals of both FGF23 and PTHi are limited by diminishing renal capacity to excrete phosphorus." (PMID 39124645, 2024). "Among biochemical parameters, hypocalcemia, hyperphosphatemia, increased fibroblast growth factor 23 (FGF23), parathormone (PTH), and alkaline phosphatase, as well as 1,25-dihydroxy vitamin D3 deficiency, are the most common findings." (PMID 36674052, 2023). "In animal models of XLH and ARHR, the global genetic deletion of Fgf23 completely suppresses FGF23 production, which results in hyperphosphatemia, hypercalcemia, increased vitamin D levels, ectopic calcifications, and early mortality." (PMID 37943605, 2023). "Second, we used inorganic phosphorus and PTH levels as indicators of physiological changes in CKD, however, the change in fibroblast growth factor 23 (FGF-23) level precedes hyperphosphatemia and is observed concurrently with PTH level elevation." (PMID 36890290, 2023).